ENSG00000284776 (novel protein)
Gene: Protein-coding gene on chromosome 20 (18,567,453 to 18,744,216, forward strand). Ensembl gene ENSG00000284776.
Genetic constraint (gnomAD): Loss-of-function variants: 11 observed, 23.28 expected, observed/expected ratio (o/e) 0.47, 90% interval 0.3 to 0.78. Missense variants: 178 observed, 237.44 expected, observed/expected ratio (o/e) 0.75, 90% interval 0.66 to 0.85. Synonymous variants: 92 observed, 91.39 expected, observed/expected ratio (o/e) 1.01, 90% interval 0.85 to 1.2.